FAM27E5 (family with sequence similarity E5)
Synonyms: MGC35151; formerly FAM27L
Gene: Long non-coding RNA gene on chromosome 17 (22,298,691 to 22,300,066, forward strand). Ensembl gene ENSG00000178130.
Diseases named in the same sentence as FAM27E5 in open-access papers:
FAM27E5 is named in the same sentence as 2 diseases in open-access papers, as found by Europe PMC text mining. Sharing a sentence is not in itself a finding about the gene and the disease.
FAM27E5 shares sentences with these, for which no sentence is quoted: cancer (1 paper); chronic myeloid leukemia (1).